PPARG (peroxisome proliferator activated receptor gamma)
Diseases named in the same sentence as PPARG in open-access papers (continued):
Sharing a sentence is not in itself a finding about the gene and the disease.
Hypertension (continued). "Another study explored perinatal melatonin therapy and found that its beneficial actions against high-fructose plus high-salt diet-induced offspring hypertension were related to regulating renal AMPKα2, AMPKβ2, SIRT1, SIRT4, PPARγ, and PGC-1α expression." (PMID 37175813, 2023). "NR3C1, REN, PPARG, and CYP11B1 were identified as critical targets (36-degree value) in the network for hypertension progression because of this conformity." (PMID 37571339, 2023). "Another study showed that the use of melatonin in gestation and lactation prevented hypertension programmed by a combined high-fructose plus post-weaning high-salt diet via regulating SIRT1, SIRT4, AMPKα2, AMPKβ2, PPARγ, and PGC-1α in the kidneys." (PMID 35624788, 2022). "A maternal methyl-donor diet led to offspring hypertension accompanied by reduced renal expression of several nutrient-sensing signaling components, comprising AMPKα2, SIRT1, PPARβ, and PPARγ." (PMID 35624788, 2022). "For example, puerarin can have an effect on 45 targets, such as VEGFA, PTGS2, AR, PPARG, and RELA, when treating hypertension." (PMID 32265716, 2020). "CYP3A4, APOA2, PPARG, ALOX, and CYP4F2, proteins related to lipid homeostasis affect the occurrence of hypertension, and PTGER2, ALOX5, LTF, ITGB, and GATA3 relate to the inflammatory and immune response in glomeruli." (PMID 30809144, 2019). "In the glomerular network, hub node PPARG was targeted by QDZJN, it has been reported to be a new target for the treatment of hypertension as well as pivotal in vascular muscle as a regulator of vascular structure, vascular function, and blood pressure." (PMID 30809144, 2019). "Peroxisome proliferator-activated receptor gamma (PPARG) plays an important role in the pathogenesis and maintenance of essential hypertension (EH)." (PMID 28727849, 2017). "In this review we summarize current knowledge about the role of PPARγ and PPARα in the functioning of the RAAS and discuss the possible modulation of RAAS­dependent hypertension by these transcription factors at the level of gene expression." (PMID 20613959, 2010). "Gene expression of RAAS molecules is modulated by PPARγ, and to a lesser extent by PPARα, making the ligands of these transcription factors potential blood pressure modulating drugs in RAAS-dependent hypertension." (PMID 20613959, 2010). "Our analyses showed that TNF, HSP90AA1, NFKB1, PPARG, SIRT1, PTGS2, and RELA might be α-MG’s potential therapeutic targets for hypertension, laying groundwork for further investigation into its pharmacological mechanisms and clinical uses." (PMID 39592923, 2024). "Moreover, treatment with a PPARγ agonist reduced RUPP-induced hypertension in an animal experiment using the reduced uterine perfusion pressure (RUPP) model, which suggests a protective role of PPARγ activity in endothelial cell function." (PMID 34830351, 2021). "Abundant clinical evidence suggest that administering PPARγ agonists, particularly thiazolidinedione (TZD) and a subgroup of angiotensin type 1-receptor blockers (ARBs), may be beneficial for patients with hypertension." (PMID 26712739, 2015). "PPARγ agonists are substances used as insulin sensitizers in diabetic patients with or without hypertension." (PMID 24454335, 2013). "In the treatment of hypertension, an increase in Na+ reabsorption via ENaC is equated with an increase in blood pressure not a decrease as seen during PPARγ agonist therapy." (PMID 20069049, 2010). "Due to inherent species differences, the mechanism of hypertension combined with MAFLD based on the (P)RR/ERK/PPARγ axis, as observed in rat and cell models, may not fully translate to human pathophysiology." (PMID 40650317, 2025). "The results indicate that in the Ang II-induced hypertension group, the expression levels of TNF, NFKB1, MAPK3, PTGS2, and RELA were markedly elevated compared to the control group, while the expression levels of HSP90AA1, HSP90AB1, PPARG, SIRT1, MAPK1, and PRKCA were significantly decreased." (PMID 39592923, 2024).
Hypertension (continued). "The PPARγ agonists rosiglitazone and pioglitazone exert beneficial effects in several aspects of PH including: suppression of pro-inflammatory cytokines such as TGF b and metalloprotease, suppression of angiotensin-II induced hypertension, and reduction of endothelin-1 levels." (PMID 33535425, 2021). "PPARG is a known regulator of glucose metabolism, thereby its synthetic ligands includes many members of the antidiabetic thiazolidinedione (TZD) drug class, glitazones and telmisartan, an antagonist of the type-1 angiotensin II receptor (AGTR1/AT1) used in the treatment of hypertension." (PMID 30419069, 2018). "So it is not a surprise that PPARγ plays important roles in CVDs including hypertension, atherosclerosis, HF, diabetic cardiomyopathy, angiogenesis, valvular calcification, aortic aneurysm, restenosis following cardiovascular interventions, and ischemia/reperfusion (I/R) injury." (PMID 27293418, 2016). "However, PPARγ agonists failed to confer antihypertensive effects in the genetic hypertension models of salt-loaded spontaneously-hypertensive stroke-prone rats (SHRSP) and fawn-hooded hypertensive rats (FHH)." (PMID 26712739, 2015). "The main reason may be that MAG just regulates the expressions of TRB3 via upregulating the transcription factor PPARγ in pathological conditions like hypertension, but do not act in normal conditions in which there is just a small quantity of TRB3." (PMID 25793876, 2015). "Several studies suggest that PPARγ is protective, as mice lacking PPARγ in the heart developed cardiac hypertrophy and dysfunction and treatment with a PPARγ agonist reduced cardiac remodeling and fibrosis in a rat model of hypertension." (PMID 24938300, 2014). "However, as direct link of hyperhomocysteinemia and hypertension is still not established, the issue of whether or not the reduction of homocysteine level through PPARγ activation reduces blood pressure remains debatable and controversial." (PMID 20613990, 2010). "Mice with cre/flox-generated endothelial- or VSMC-specific PPARγ deficiency have also been shown to develop hypertension, although no histology was presented for these models and their vasodilator and vasoconstrictor responses were opposite to those reported for the VSMC DN-PPARγ mouse model." (PMID 20300579, 2009). "Although it has not been reported about PPARγ agonist, a previous study revealed that treatment with GW1929, a selective PPARγ antagonist, enhanced PPARγ mRNA expressions in kidneys from hypertension model rats." (PMID 22003398, 2011).
prostate carcinoma (139 papers, 2000 to 2025). A carcinoma that arises from epithelial cells of the prostate gland. "In MR analysis, genetically proxied PPARG perturbation was weakly associated with higher risk of prostate cancer (for PPARG perturbation equivalent to a 1 unit decrease in inverse rank normal transformed HbA1c: OR 1.75 [95% CI 1.07, 2.85], p=0.02)." (PMID 37171501, 2023). "Results here would confirm recent evidence suggesting that PPARγ is generally associated with a poor prognosis in prostate cancer, since it is related to an increase in AKT expression and further mitogenesis or other AR-dependent and independent mechanisms." (PMID 37770940, 2023). "Nonetheless, activated PPARγ mutations have also been discovered and are linked to cancer initiation in bladder and prostate cancer." (PMID 36142452, 2022). "The gene pairs exclusively identified by the SIG method unravel mechanisms for PPARG function loss during prostate cancer development." (PMID 19640296, 2009). "Since both GR and PPARγ have been linked to enhanced tumor growth, the increased expression of these nuclear receptors may help prostate cancer cells to overcome metformin-induced reductions in AR." (PMID 36175875, 2022). "Besides its roles in adipocyte differentiation and lipid metabolism, we recently demonstrated an association between PPARG and metastasis in prostate cancer." (PMID 33654198, 2021). "Furthermore, our data show that warfarin inhibits PPARγ and AR signaling, which suggests that inhibition of these pathways could be used to reduce the risk of developing prostate cancer." (PMID 28099154, 2017). "PPARγ activation has been implicated to inhibit the proliferation of malignant cells from different lineages such as liposarcoma, breast adenocarcinoma, prostate carcinoma, colorectal carcinoma, non-small-cell lung carcinoma, pancreatic carcinoma, bladder cancer cells, and gastric carcinoma cells." (PMID 23213321, 2012). "This study aimed to analyze the individual or combined effects of I2 and androgen deprivation on prostate cancer and to assess the role of PPARG in these projections." (PMID 40869121, 2025). "FABP5 promotes prostate cancer proliferation and invasion by regulating lipid metabolism and the PPARγ signaling pathway." (PMID 40717587, 2025). "The expression and transcriptional activity of PPARG can be inhibited by AR in human prostate cancer cells." (PMID 40458476, 2025). "For instance, treatment with the PPARγ agonist pioglitazone has been shown to reduce tumor growth in a metastatic PC3 prostate cancer xenograft model, accompanied by increased phosphorylation of AMPKα and decreased phosphorylation of mTOR." (PMID 41476922, 2025). "Consistently, a previous study showed that cytokines, a lipogenic environment, and PPARG activation are essential for neurite-like projection growth in prostate cancer cells." (PMID 40869121, 2025). "We investigated the adjuvant effects of I2 and androgen deprivation in prostate cancer, as well as the role of PPARG in these projections." (PMID 40869121, 2025). "To test this, we evaluated cell viability, invasive capacity, and the acquisition of a NE-like phenotype in prostate cancer cell lines cultured under androgen-deprived conditions and in the presence of a PPARG selective antagonist." (PMID 40869121, 2025). "FABP12 promotes migration and invasion of prostate cancer (PCa) cells by activating the PPARγ signaling pathway, inducing epithelial-mesenchymal transition (EMT)." (PMID 40717587, 2025). "On the other hand, in advanced prostate cancer, the androgen receptor blockade enhances PPARG lipogenic signaling and the acquisition of a prostate NE phenotype, revealing mutual interrelationships." (PMID 40869121, 2025). "Investigations have revealed that activation of PPARγ in prostate cancer cells increased mitochondrial biogenesis and ATP levels by upregulating AKT3, which enhanced the nuclear localization of PGC1α." (PMID 39791746, 2025).
prostate carcinoma (continued). "Much attention has been paid to the role of PPARs in oncogenesis, including PPARδ in human endometrial adenocarcinoma and colorectal cancer and PPARγ in gastric or prostate cancer." (PMID 39062500, 2024). "A possible role of reduced PPARγ activation by 15-HETE in the development or progression of prostate cancer has been suspected." (PMID 39062500, 2024). "Previous studies have shown that PPARG gene expression levels are significantly upregulated in bladder cancer, esophageal adenocarcinoma, and prostate cancer." (PMID 38044948, 2023). "This is apparent since the dose used in vitro is far higher than that required to activate PPARγ, and appears to impair prostate cancer cell growth." (PMID 36510001, 2023). "LncRNA PRRT3-AS1 is able to inhibit the PPARγ gene to promote prostate cancer cell proliferation and inhibit apoptosis and autophagy by activating the mTOR signaling pathway." (PMID 36647032, 2023). "Since then, two decades of scientific research have improved our understanding of PPARγ, and ongoing research continues to highlight the role of PPARγ in prostate cancer." (PMID 36510001, 2023). "A growing body of research has demonstrated that peroxisome proliferator-activated receptor gamma (PPARγ) is amplified as prostate cancer progresses." (PMID 36510001, 2023). "PPARγ has been shown to support prostate cancer growth through its roles in fatty acid synthesis, mitochondrial biogenesis, and co-operating with androgen receptor signalling." (PMID 36510001, 2023). "A recent in vitro study shows that the synthesis of lipid droplet and the proliferation and migration of prostate cancer cells activated by the PPARγ pathway can be effectively promoted by low-dose rosiglitazone." (PMID 37560306, 2023). "In fact, an increased level of PPARγ expression was observed in prostate cancer and was positively correlated with stage and grade of prostate cancer, and thus PPARγ has been considered as an oncogene." (PMID 36358965, 2022). "Data from cBioPortal reveal that the PPARG gene is amplified or upregulated in a subset of castration-resistant prostate cancers." (PMID 36175875, 2022). "N-3 polyunsaturated fatty acids stimulated Syndecan 1 expression via PPARγ activation in prostate epithelium and prostate cancer cells." (PMID 35954274, 2022). "We believe that this is due in part to metformin-induced decreases in AR activity, for expression of PPARγ and GR is suppressed by AR in human prostate cancer cells." (PMID 36175875, 2022). "PPARγ can function as a tumor suppressor, for loss of PPARγ within the mouse prostate results in the development of prostate intraepithelial neoplasia (PIN), a precursor to prostate cancer." (PMID 36175875, 2022). "Although data regarding the subcellular localization of PPARγ in bone tumors is limited, the cytoplasmic localization of PPARγ was reported in other types of tumors such as prostate cancer." (PMID 35922782, 2022). "siRNA knockdown of PPARγ and treatment of PPARγ antagonist (warfarin) led to reduced prostate cancer tumor size and thus inhibited prostate cancer cell growth." (PMID 36358965, 2022). "The PPARγ agonist troglitazone inhibited the proliferation of PC-3 prostate cancer cells in vitro and in xenograft models in vivo, which was confirmed by others in later studies." (PMID 35954274, 2022). "PPARγ was once considered to be a tumor suppressor, and thus PPARγ agonists such as troglitazone were used to treat prostate cancer in clinical trials." (PMID 36358965, 2022). "It is therefore important to note that in Jurkat lymphoma and prostate cancer cells, 15d-PGJ2 elevation was associated with PPARγ independent increases in protein levels of DR5 mediated by mRNA stabilization, potentiating TRAIL-induced apoptosis." (PMID 33289496, 2021). "It has also been reported as a relevant factor in prostate cancer, although it can have opposing effects depending on the stage and on PPARγ status." (PMID 33333852, 2020).
prostate carcinoma (continued). "PPARγ was originally thought to exert antioncogenic properties in prostate cancer because PPARγ agonists inhibited the growth of prostate cancer cells." (PMID 31212954, 2019). "Another clinical trial also tested a combined therapy with PPARγ agonist (rosiglitazone/pioglitazone), fenofibrate, and calcitriol in castration-resistant prostate cancer, but was terminated early due to low accrual (EUCTR 2006-001398-44)." (PMID 31614690, 2019). "PPARγ is a receptor for fatty acids localised in the nuclear membrane and this receptor plays an important role in promoting metastasis in prostate cancer." (PMID 31258834, 2019). "In fact, a number of recent studies have confirmed the promoting role of PPARγ in malignant progression of prostate cancer and that the stimulation produced by FABP5- transported fatty acids plays an important role in PPARγ activation." (PMID 31258834, 2019). "In the context of prostate cancer, Ahmad and co-workers found that PPARγ-mediated expression of FAS sustains the growth of prostate cancer cells and confers poor prognosis for metastatic prostate cancer." (PMID 31922096, 2019). "PPARγ agonists as a monotherapy for maintenance therapy was studied during prostate cancer remission." (PMID 31614690, 2019). "NCOR, a repressor of PPARγ, has been found to increase in prostate cancer and to inhibit the expression of PPARγ." (PMID 29706964, 2018). "Previous studies have shown that the activation of nuclear receptors PPARγ and LXRα is related to the growth inhibition of prostate cancer." (PMID 29573196, 2018). "It has been demonstrated that lycopene inhibits prostate cancer cell proliferation via the PPARγ-LXRα-ABCA1 pathway." (PMID 29324670, 2018). "On the other hand, activation of AR reduces PPARγ levels and activity within human prostate cancers." (PMID 29181019, 2017). "A similar phenotype was observed with the inhibition of PPARγ in castration-resistant prostate cancer cells." (PMID 28099154, 2017). "This review will discuss our current understanding of the role of AR and PPARγ within the prostate and how interactions between these two signaling pathways can influence the growth and development of normal prostate as well as prostate cancer." (PMID 29181019, 2017). "This suggests that any reduction in AR signaling would increase the amount of functional PPARγ and enhance the antitumor effects of PPARγ within prostate cancers." (PMID 29181019, 2017). "Compounds that have been identified as ligands for PPARγ appear to use PPARγ-dependent as well as PPARγ-independent signaling pathways to regulate prostate cancer growth." (PMID 29181019, 2017). "PPARγ mRNA and protein have been detected in castration-sensitive as well as castration-resistant prostate cancer cell lines." (PMID 29181019, 2017). "Both PPARγ mRNA and protein have been detected within human prostate tumor tissue sections and prostate cancer cell lines." (PMID 29181019, 2017). "In this review, we examine how AR and PPARγ each regulate the growth and development of normal prostatic epithelial cells and prostate cancers." (PMID 29181019, 2017). "Crosstalk between the AR and PPARγ signaling pathways can also be influenced by the amount of each receptor present within human prostate cancer cells." (PMID 29181019, 2017). "It is possible that AR uses at least two different strategies to control metabolism in prostate cancers cells: the direct regulation of AR target genes and modulation of PPARγ function." (PMID 29181019, 2017). "The AR agonist DHT at nanomolar concentrations produced a significant decrease in PPARγ mRNA and protein levels within two AR-positive human prostate cancer cell lines: the castration-sensitive VCaP cells and castration-resistant C4-2 cell line." (PMID 29181019, 2017). "In prostate cancers, the ability of PPARγ to regulate AR function varies depending on the ability of tumors to respond to castration." (PMID 29181019, 2017).